CD36 (CD36 molecule (CD36 blood group))
Diseases named in the same sentence as CD36 in open-access papers (continued):
Sharing a sentence is not in itself a finding about the gene and the disease.
tumor (continued). "Consistent with redirection of TAM activation from tumor-promoting to tumor-inhibiting, expression of CD36, which is upregulated on immunosuppressive breast TAMs27, was significantly attenuated by CDDO-Me." (PMID 32300202, 2020). "In contrast to these findings, our study suggests a critical role of CD36 in CRC proliferation and tumor growth in vivo with both chemical inhibition via SSO as well as shRNA-mediated knockdown of CD36 in xenografts using multiple established cell lines." (PMID 32850342, 2020). "Investigation of CD36 in cancer revealed the role of CD36 in tumor metabolism, as well as in tumor immuno-editing, anti-angiogenic processes, metastasis, or therapy resistance." (PMID 32781778, 2020). "CD36 has been found to be crucial for lipid metabolism in these cells and enables them to suppress immune responses in the tumor microenvironment." (PMID 33086598, 2020). "Oleic acid, the principal lipid in olive oil, can upregulate the expression of CD36 and facilitate tumor development by activating the Src kinase and the downstream ERK1/2 pathway in a CD36-dependent manner." (PMID 33364199, 2020). "Although we did not observe a significant difference in MYC (p = 0.08) or LPL (p = 0.11) expression between basal-TNBC and CL-TNBC, we did find that CL-TNBC tumours had significantly higher expression of CD36 (p < 0.0001) and PDGFRB (p < 0.0001)." (PMID 31942031, 2020). "CD36 plays an important role in cancer by accelerating tumor growth and metastasis, and modulating the immune response and response to therapy, and has thus been a target for cancer treatment." (PMID 33123499, 2020). "Collectively, these findings demonstrate that FATBPs and CD36 play a key role in tumor microenvironment metabolic cross-talk, driving the dependency of tumor cells toward exogenous lipid rewiring cancer cell metabolism and behavior." (PMID 32266157, 2020). "Regarding ncRNAs over this point, a role of miR-1254 as a tumor suppressor in oral squamous cell carcinoma mediated by the direct inhibition of the expression of CD36 has been reported." (PMID 33050166, 2020). "Targeting the fatty acid transporter CD36 almost completely inhibited tumor metastasis in mice model." (PMID 31740790, 2020). "CD36 has also been revealed to play roles in other important cellular processes related to tumor biology, including angiogenesis, antigen presentation and cell adhesion." (PMID 33226369, 2020). "shRNA-mediated knockdown of CD36 and inhibition of CD36 via sulfosuccinimidyl oleate, a chemical inhibitor of CD36, decreased cell proliferation in vitro and reduced tumor growth in subcutaneous xenograft models." (PMID 32850342, 2020). "The tumour promoting effect of PA via CD36 was reported in gastric cancer cells too, and PA induced metastasis by phosphorylation of protein kinase B (AKT), leading to activation of AKT/ glycogen synthase kinase-3 beta (GSK-3β)/β-catenin signalling pathway." (PMID 32526973, 2020). "CD36 is at the apex of a signaling cascade involved in lipid uptake and storage, through which it has recently been shown to enable tumor metastasis." (PMID 32273287, 2020). "Nobiletin inhibits CD36-dependent tumor angiogenesis, migration, invasion and sphere formation through the CD36/Stat3/Nf-Κb signaling axis." (PMID 32503228, 2020). "In vivo mice liver macrophages and in vitro myeloid immune cells studies confirmed the important role of CD36 in tumor microvesicles mediation." (PMID 32781778, 2020). "Tregs situated in tumors increased both the expression of the fatty acid receptor, CD36, and lipid uptake, leading to a PPARβ-driven increase in capacity to survive in lactic acid-rich tumor microenvironments." (PMID 33604295, 2020). "Fatty acid transporter proteins (CD36, Fabp1, Slc27a4) mediate the uptake of fatty acids and were reported to be highly expressed in cancer cells and to function in tumor growth." (PMID 32156004, 2020).
tumor (continued). "Leukemic-CSCs with increased FAO and upregulated CD36 (FA transporter) expression exhibit chemoresistance while in vivo and ex vivo studies with CD36 knockout cells showed decreased tumor size when injected in mice." (PMID 32670883, 2020). "In RCC tumor cells, both CD36 and FATP4 revealed predominant membranous expression, which was significantly higher than in normal cells, and showed loss of the site-specific localization pattern found in normal cells." (PMID 31089396, 2019). "In tumor tissues, CD36 is expressed in tumor cells and in stromal and immune cells, but the expression level varies in distinct cell types and tumor stages." (PMID 31410189, 2019). "As a scavenger receptor, CD36 exhibits high affinity to transport LCFAs, which contribute to tumor growth." (PMID 31410189, 2019). "Genetic depletion of the fatty acid translocase CD36 inhibits the induction of immunosuppressive function in tumor-infiltrating Myeloid-derived suppressor cells (MDSC) and results in a CD8+ T cell-dependent delay in tumor growth." (PMID 31074374, 2019). "Increased fatty acid uptake based on the high membranous expression of FATP4 and CD36 can be specifically targeted in RCC tumor cells in combination with other therapies against altered lipid metabolism." (PMID 31089396, 2019). "In tumor tissues, CD36 is expressed in tumor cells 4, MVECs 17, stromal cells 5, and immune cells 18, and the CD36 level varies in distinct cell types." (PMID 31410189, 2019). "Taken together, these results further suggested the molecular mechanism by which CD36 controls tumor proliferation and glycolysis via inhibiting GPC4-mediated β-catenin/c-myc signaling in colorectal tumorigenesis." (PMID 31484922, 2019). "Mouse studies suggest that, at least in some cancers, cells with tumor-initiating capacity express CD36 (which is a fatty acid receptor) and that stimulation of CD36-expressing cells with the fatty acid palmitate increased metastasis size and frequency." (PMID 31296202, 2019). "In recent decades, in-depth research on CD36 in cancer has elucidated CD36 functions in tumor-cell metabolism, anti-angiogenesis, metastasis, therapy resistance, and tumor immunoediting." (PMID 31410189, 2019). "For instance, in a cervical cancer xenograft model, a high oleic acid diet increases tumor volume and weight, and inhibition of CD36 prevents this effect." (PMID 31410189, 2019). "Here, we report a progressively decreased expression and a tumor-suppressive role of CD36 in CRC development." (PMID 31484922, 2019). "After 5 weeks (consistent with in vitro data), we observed that overexpression of CD36 significantly promoted tumor growth in female BALB/c-nu mice." (PMID 31655604, 2019). "Genetic depletion of the fatty acid translocase CD36 in tumor-bearing mice delayed tumor growth in vivo." (PMID 31616408, 2019). "In our study, CD36 overexpression in C33a cells facilitated proliferation and invasion in vitro and aggravated tumor metastasis in a xenograft mouse model." (PMID 31655604, 2019). "In this study, increased membranous CD36 was not clinically significant in RCC, although a higher membranous expression of CD36 was revealed in tumor tissues than in normal cells." (PMID 31089396, 2019). "GBM stem cells expressing high levels of CD36 were found to enhance self-renewal and tumor initiation." (PMID 31410189, 2019). "Clinically, CD36 expression in tumor cells has been proposed to induce tumor progression in various human cancers." (PMID 31089396, 2019). "This tumor-promoting effect of PA was mediated by CD36, a cell surface receptor of fatty acids (FAs)." (PMID 30717785, 2019). "In GBM stem cells, CD36 is co-expressed with integrin-6 and CD133, and a decrease in CD36 results in the loss of integrin-6 expression, self-renewal, and tumor initiation." (PMID 31410189, 2019).
tumor (continued). "In this study, we observed that O-GlcNAcylation-activated NF-κB accelerated CD36 transcription, suggesting that the tumor-promoting role of CD36 is at least partly dependent on O-GlcNAcylation-mediated NF-κB activation." (PMID 31410220, 2019). "CD36 is a membrane glycoprotein that has been shown to have tumour promoting or suppressor function depending on tumour type." (PMID 31484922, 2019). "Deep sequencing of the miRome pointed to enhanced accumulation of miR-375 in TAMs, facilitated by the uptake of tumor-derived miR-375 via CD36." (PMID 30850595, 2019). "To test our idea, we generated GPC4-overexpressed plasmids to examine the importance of GPC4 in CD36-mediated tumor-suppressive function." (PMID 31484922, 2019). "We also revealed lipid metabolism biomarkers that were closely correlated with the tumor immune microenvironment, such as CD36." (PMID 31074374, 2019). "CD36 expressed on specific tissue immune cells bind and engulf tumor microvesicles, which leads to the invasion and extravasation of microvesicles from vessel walls and promotes metastasis." (PMID 31410189, 2019). "On the other hand, comprehensive functional experiments are needed: eg it will be interesting to select CD44+/CD133+/ITGA6+/CD36+ cells and to evaluate their tumor formation capacity in NOD‐SCID mice brains." (PMID 30467961, 2019). "To further verify the regulatory features of CD36 in vivo, we introduced AAVs into the ApcMin/+ mice with vein injection and examined the tumor growth." (PMID 31484922, 2019). "Although several preclinical studies and clinical trials targeting CD36 for cancer treatment are being performed, further studies are needed to explore the effects of CD36 on innate immune cell-mediated anti-tumor functions." (PMID 31847240, 2019). "Recently, several preclinical and clinical studies demonstrated that upregulation of CD36 is a prerequisite for tumor metastasis." (PMID 31379931, 2019). "In vivo experiments demonstrated that CD36 knockdown or treatment with a neutralizing antibody significantly reduced tumor burden and metastatic nodules in intraperitoneal OC xenograft models." (PMID 31769430, 2019). "Nobiletin, a flavonoid isolated from citrus peel, was shown to block STAT3 binding of the GAS element and CD36 promoter and thereby inhibit angiogenesis, tumor invasion, and metastasis." (PMID 31410189, 2019). "The cluster of differentiation 36 (Cd36) was identified as the most stimulated gene, which was also confirmed using additional normal and tumor tissues by qRT-PCR and western blot analysis." (PMID 31358770, 2019). "STAT3 interacted with CD36, which then interacted with NF-κB; thus, nobiletin inhibited tumor angiogenesis via the CD36/STAT3/NF-κB signaling axis." (PMID 29914089, 2018). "CD36 plays a role in tumor angiogenesis by binding to its ligand, thrombospondin-1 (TSP-1), and then interacting with transforming growth factor beta 1 (TGFβ1)." (PMID 29914089, 2018). "Recently, tumor cell metastasis in mice was found to be under strong control of the tumor cells’ potential to express the fatty acid receptor CD36 and metabolize fatty acids." (PMID 29697773, 2018). "Data from animal models and in vitro human tumour cell lines point to CD36 as a metastasis-related indicator, prompting investigations on a larger scale in human tumour samples." (PMID 30069479, 2018). "We showed that CD36 can regulate tumor metastasis and tumor sphere formation in cells treated with PA." (PMID 29914089, 2018). "CD36 acts as a fatty acid receptor and plays a key role in tumor metastasis by regulating lipid metabolism." (PMID 29914089, 2018). "Accordingly, we analyzed the role of CD36 in tumor migration and invasion and found that nobiletin inhibited CD36-dependent tumor migration and invasion." (PMID 29914089, 2018). "In tumors with high frequency of bone metastasis, BMAs exert its pro-tumor effects mainly by modulating lipid metabolism associated genes, including FABP4, PPARγ and CD36." (PMID 30013512, 2018).
tumor (continued). "Treatment with CD36 siRNA inhibited cell invasion by almost 65%, suggesting that CD36 plays a role in tumor metastasis." (PMID 29914089, 2018). "Recently, a study addressed directly the involvement of CD36 in tumour growth and metastasis, by overexpressing CD36 in oral squamous carcinoma cell lines." (PMID 30069479, 2018). "The probability with the same value of recurrence-free survival (RFS) was higher in ER- or Her2-positive patients with low tumor CD36 expression than patients having high CD36 expression (p = 0.039 or 0.0017)." (PMID 30573731, 2018). "The free fatty acids (FFAs) released by adipocytes after lipolysis induced by tumour secretions are transferred and stored in tumour cells as triglycerides in lipid droplets, a process dependent on CD36 expression levels." (PMID 29266765, 2018). "Only a handful of papers have been published directly addressing CD36, almost all measuring levels of expression in relationship to tumour growth and metastasis." (PMID 30069479, 2018). "Correlated with invasion of tumours and metastasis, CD36 has been repeatedly proposed as a prognostic marker in various types of cancers, mostly of epithelial origin." (PMID 30069479, 2018). "We found that nobiletin inhibited the expression of these tumor marker genes, suggesting that nobiletin inhibited CD36-mediated tumor sphere formation." (PMID 29914089, 2018). "The role of CD36 in cell growth or resistance to tamoxifen treatment is correlated with CD36-mediated uptake of fatty acids to satisfy the activated metabolic status of tumor cells." (PMID 30573731, 2018). "Functionally, COMP/CD36 signaling caused phosphorylation of ERK and AKT, resulting in the upregulation of tumor-progressive genes such as EMT markers, MMP-2/9, Slug and Twist in HCC cells." (PMID 30231922, 2018). "Once CD36 was inhibited by CD36-neutralizing antibodies, large lipid-abundant tumor cells would appear, as well as a significantly reduced incidence of metastasis." (PMID 30013512, 2018). "CD36 is a basic marker for cancer cells that plays important roles in tumor angiogenesis and tumor metastasis." (PMID 29914089, 2018). "In contrast, consistent with data from tumour growth mechanism studies, CD36 has been reported to be decreased in endothelial cells, as a bypass program of its antiangiogenic effect." (PMID 30069479, 2018). "In metastatic prostate cancer, CD36 was activated in tumour cells, which led to increased cell migration and invasion, linked to downstream activation of MAPK." (PMID 30069479, 2018). "Together, these results presented that functional significance of CD36 was involved in the COMP induced tumor grwoth and metastasis of HCC." (PMID 30231922, 2018). "Though MYC is not necessary for hepatoblastoma development, depletion of MYC delays tumor progression through reducing fatty acid transporter CD36 expression, with a concomitant decrease in LDs accumulation and FAO levels." (PMID 29907133, 2018). "Some proteins that are involved in fatty acid metabolism are also involved in CD36-mediated tumor-promoting activities that are inhibited by nobiletin." (PMID 29914089, 2018). "Inhibiting STAT3 or STAT5 signaling or knockout of CD36, a fatty acid translocase, can prevent lipid metabolism and thus the immunosuppressive functions of MDSCs in the tumor environment." (PMID 30619850, 2018). "The results showed that CD36 knockdown attenuated the effect of rCOMP-induced promotion of tumor cell proliferation and lung metastasis (P < 0.05)." (PMID 30231922, 2018). "It was shown that tumor-infiltrating MDSC displayed an upregulation of the fatty acid translocase, CD36, which resulted in an increased uptake and oxidation of fatty acids." (PMID 29552012, 2018). "Recent studies suggest that CD36 overexpression induces tumor metastasis by affecting lipid metabolism." (PMID 29914089, 2018).
tumor (continued). "To support our finding of CD36 expression in tumor endothelium in vivo, we first studied the expression of this molecule in TAECs in response to LPA treatment." (PMID 28186980, 2017). "Similar to previous studies in breast and other cancer types, we observed enhanced vascular expression of aSMA and VEGFR2 along with CD36 downregulation in certain tumor vessels." (PMID 28186980, 2017). "CD36 expression was repressed in a range of stromal cell types (fibroblasts, adipocytes, endothelial cells) in both tissues of high MD and in tumour stroma." (PMID 26784251, 2016). "It plays a functional role in inhibiting tumor growth, cell migration, and neovascularization; it also acts as an endogenous tumor suppressor by interacting with its receptors, CD36 and CD47, or activating transforming growth factor-beta signaling." (PMID 27513329, 2016). "This was further confirmed by significantly increased gene expression of lipid droplet marker perilipin 2 and lipid transporter CD36 in tumor cells exposed to adipocytes both in the absence and presence of Atglistatin." (PMID 27588494, 2016). "We next performed the multivariate regression analysis controlling for sex and tumor grade and found that both ZEB1 (p = 2.2 × 10−7) and ZEB2 (p = 0.006) were significantly associated with the expression levels of CD36 in the human protein samples." (PMID 26424075, 2015). "By modulating endothelial cell proliferation and migration as well as apoptosis in CD36-expressing cancer cells, ABT-510 targets both tumor cells and the associated tumor vascular network." (PMID 26046793, 2015). "In order to reach an optimal control of tumor progression, future directions will aim to associate innovative approaches targeting TSP-1/CD47 and TSP-1/CD36 signaling with existing anticancer treatments." (PMID 26578962, 2015). "Specifically, genes that allow tumour cells to interact with extracellular components, such as syndecan 2 and CD36, were lower in cell lines than in tumours." (PMID 26289960, 2015). "In ovarian tumor development, we demonstrated that treatment with TSP-1 mimetic peptides inhibited tumor formation, and that this effect was abrogated when CD36 expression was knocked down." (PMID 24628875, 2014). "Knockdown of CD36 has been shown to increase proliferation and expression of survival and angiogenic in endothelial and tumor cells." (PMID 24628875, 2014). "In contrast, secretion of TSP-1 by activated stromal cells including fibroblasts inhibits tumor growth by binding to CD36 on the surface of endothelial cells and promoting apoptosis." (PMID 26273699, 2014). "The importance of the TSP1/CD36 pathway has been proven in tumorigenesis, where down regulation of TSP-1 and its binding to CD36 results in a pro-tumorigenesis environment and increase in tumor size." (PMID 23405239, 2013). "As predicted by our model tumor growth was increased in cd36 null mice and decreased in hrg null mice." (PMID 22808089, 2012). "Mean tumor volumes in cd36 null vs wildtype mice were 21.0 mm3 vs 15.8 mm3 at day 7, 100.4 mm3 vs 52.1 mm3 at day 10, 213.6 mm3 vs 136.3 mm3 at day 14 and 316.2 mm3 vs 237.7 mm3 at day 17 respectively." (PMID 22808089, 2012). "Average tumor volume in cd36 null vs wildtype individuals were 27.8 mm3 vs 17.5 mm3 at day 8 (P = 0.08); 67.7 mm3 vs 37.8 mm3 at day 11 (P<0.05); 170.5 mm3 vs 98.0 mm3 at day 14 (P<0.05); and 685.1 mm3 vs 394.7 mm3 at day 18 (p = 0.06)." (PMID 22808089, 2012). "In the present manuscript we show that genetic deletion of cd36 or hrgp in C57BL/6 mice effected tumor growth and vascularity." (PMID 22808089, 2012). "Pharmacological modulation of lipid-driven signaling pathways through CCR5 inhibition (inflammation modulation through maraviroc) or blockade of the lipid scavenger receptor CD36 reprograms TAMs, restores T cell activity, and enhances antitumor immune responses within lipid-rich tumor niches." (PMID 41775684, 2026).